CTLA4 (cytotoxic T-lymphocyte associated protein 4)
Diseases named in the same sentence as CTLA4 in open-access papers (continued):
Sharing a sentence is not in itself a finding about the gene and the disease.
tumor (continued). "Ketogenic diets that significantly lower glucose levels in vivo, when combined with the anti‐CTLA‐4 antibody, markedly retarded tumour progression by decreasing PD‐L1 expression and promoting antitumour immunity pathways." (PMID 39754316, 2025). "On the other hand, PD-1 and CTLA-4 are co-expressed in a high percentage of tumor-infiltrating lymphocytes." (PMID 40510353, 2025). "Evidence indicates that ICIs enhance anti-tumor immunity by modulating the PD-1/PD-L1 and CTLA-4/CD80/86 pathways, strengthening tumor antigen recognition and ultimately inducing tumor cell death." (PMID 41244814, 2025). "In several animal model experiments, blocking CTLA-4 has been shown to effectively enhance anti-tumor effects." (PMID 40066456, 2025). "Blockade of the PD-1/PD-L1 axis mainly eliminates T cell exhaustion within the tumor microenvironment, while blockade of CTLA-4 promotes the efficient activation and clonal expansion of naive T cells in peripheral lymph nodes." (PMID 41415276, 2025). "In tumor cells, B7 is overexpressed, recognizing and binding to CTLA-4, downregulating the immune response of T cells, and leading to immune escape." (PMID 40270890, 2025). "Among the various combinations being studied, the concurrent administration of anti-PD-1 (NIV) anti-CTLA-4 (IPI) has exhibited notable efficacy in tumor treatment." (PMID 41237182, 2025). "In both cell lines tested, the team observed that the combination of their PCI treatment and anti-CTLA-4 significantly reduced tumor burden and increased tumor clearance in mice." (PMID 41180369, 2025). "Tumor cells express surface molecules critical to tumor immunity, including immune checkpoints such as PD-L1, CTLA-4, and V-domain Ig suppressor of T cell activation (VISTA)." (PMID 39987091, 2025). "An accumulation of FoxP3+ immune cells (Tregs), potentially acting through the CTLA-4 immune checkpoint, appears to contribute to immunosuppression, tumor progression, and metastasis." (PMID 41230456, 2025). "KP Ova, despite expressing the ova model antigen, which is capable of being recognized by T cells, is an “immune cold” tumor that is unresponsive to anti-PD-1 plus anti-CTLA4 immune checkpoint inhibition." (PMID 41010344, 2025). "Regulatory T cell (T-reg) exert negative regulatory effects in tumor immunotherapy, with immune checkpoints such as CTLA-4 and PD-1 selectively overexpressed on TME-resident T-reg cells." (PMID 40575167, 2025). "Immune checkpoint inhibitors (ICIs) block inhibitory receptors such as CTLA-4, PD-1, and PD-L1 on immune cells, effectively activating the immune system to attack tumor cells." (PMID 40242775, 2025). "For instance, sCTLA-4, a soluble form of CTLA-4, has been identified as a significant modulator of anti-tumor immune responses." (PMID 40739089, 2025). "The immune checkpoint blockade targeting PD-1, PD-L1, and CTLA-4 functions by disrupting inhibitory pathways that tumors exploit to evade anti-tumor detection and destruction." (PMID 40565041, 2025). "CTLA-4+ TILs were observed in 69.4% of FMCs, while only 4.1% of tumor cells were positive for the marker." (PMID 41150099, 2025). "ICB therapy reduces tumor-induced immunosuppression by blocking immune checkpoint molecules, such as PD-1/PD-L1 and CTLA-4, allowing immune cells to exert their antitumor activity." (PMID 40038799, 2025). "In contrast, the tumor areas commonly expressed high CTLA4, low PD‐L1 and CD274, and very low IDO1 in sample HCC3." (PMID 41057994, 2025). "Further, a clinical drug screening showed Clofazimine potentiates the anti-tumor efficacy and reduces the toxicity of dual anti-PD-1 and CTLA-4 immune checkpoint blockade (ICB)." (PMID 41303378, 2025). "The combination therapy, which often includes drugs such as nivolumab (anti-PD-1) and ipilimumab (anti-CTLA-4), works by simultaneously ‘priming’ and ‘enhancing’ T-cell responses to release an antitumor potential against the tumor." (PMID 41369373, 2025).
tumor (continued). "MNX1 ablation activates cytotoxic T cell‐mediated anti‐tumor immunity and sensitizes CTLA‐4 blockade therapy." (PMID 39912421, 2025). "In this immunosuppressive microenvironment, the immune checkpoints CTLA4 and PD-1 are upregulated, and regions with a high bacterial load in the tumor form a barrier that hinders the infiltration of T cells into the tumor." (PMID 39966840, 2025). "For example, succinate can enhance the infiltration of cytotoxic T-lymphocyte-associated protein 4 (CTLA-4) positive T cells by interacting with its receptor SUCNR1, thus modifying the immune milieu of the tumor microenvironment." (PMID 41049851, 2025). "Recent studies implicate loss of immune tolerance through PD-1/PD-L1 or CTLA-4 blockade, expansion of autoreactive CD8+ T cells, cross-reactivity between tumor and cardiac antigens, and downstream inflammatory cascades as central drivers of myocardial injury." (PMID 41394853, 2025). "Although OVV-mNbTIM3 cured 80% of the mice’s tumors, combination therapy with anti-PD-1 or anti-CTLA4 further promoted complete tumor remission in mice, achieving 100% or 90% remission rates respectively." (PMID 41291902, 2025). "Here, we report that intratumoral MMR therapy in a mouse model of HCC not only suppressed tumor growth and extended survival but also synergized with anti-PD-1 and anti-CTLA-4 blockade to remodel the protumorigenic TME." (PMID 41142777, 2025). "Congruent with our current results, the therapeutic effect of anti-PD-1 and anti-CTLA4 was conditional on a CD4-driven anti-tumor response, while depletion of CD4+ cells still had a less pronounced effect on overall survival than depletion of CD8+ cells." (PMID 40102596, 2025). "Immunotherapies, notably immune checkpoint inhibitors (ICIs), treat solid tumors by enhancing T cell activation and blocking inhibitory receptors like PD-1 or CTLA-4, strengthening immune attacks on tumor cells." (PMID 39996827, 2025). "Currently, research on immune checkpoint inhibitors like PD-1 inhibitors, PD-L1 inhibitors, CTLA-4 inhibitors, and the tumor immune microenvironment has become a hot topic." (PMID 40963868, 2025). "Therapeutically, tumors with high PANoptosis scores exhibit greater tumor mutation burden (TMB), enhanced infiltration of CD8+ T and dendritic cells, and higher objective response rates (ORR) to PD-1/CTLA-4 inhibitors (42% vs 18%)." (PMID 41583472, 2025). "which can act on both programmed cell death protein 1 (PD-1) and cytotoxic T lymphocyte-associated antigen 4 (CTLA-4) receptors, and can multivalently bind to T cells that coexpress PD-1 and CTLA-4 in the tumor microenvironment." (PMID 40115023, 2025). "In melanoma models, tumor prognosis was somewhat improved by enhanced immune activity following anti-CTLA-4 therapy." (PMID 40420174, 2025). "Researchers combined the demethylating drug 5-aza-2’-deoxycytidine (5DC) with CTLA-4 blockade to enhance the immune response against MAGE-A-expressing tumor cells." (PMID 40281554, 2025). "This phenomenon, observed in recent studies, underscores the potential of CTLA-4 inhibitors to reshape the immune landscape and bolster anti-tumor immunity." (PMID 40305346, 2025). "Compared with traditional PD-1+CTLA-4 monoclonal antibody combination therapies, cadonilimab can accurately target tumor-infiltrating lymphocytes due to its unique molecular structure." (PMID 40755777, 2025). "Multichannel immunofluorescence with the T-cell marker CD3 confirmed that the majority of double-positive CTLA4+IFN-γ+ cells across all tumor types were T lymphocytes." (PMID 40005446, 2025). "The discovery achieved by Prof. Allison's group that the CTLA-4 blockade enhances the anti-tumor immunity in a murine model, offers a novel perspective on cancer therapeutic approaches." (PMID 41141615, 2025). "This highlights CTLA-4 blockade as a promising therapeutic strategy to unleash anti-tumor immunity by targeting the CTLA-4 axis within the TME." (PMID 40281554, 2025).
tumor (continued). "CTLA-4 is an immune checkpoint molecule that is expressed on tumor cells and immune cells and inhibits the activation and proliferation of T cells." (PMID 40850976, 2025). "For instance, miR-138 suppresses CTLA-4 and PD-1 in T cells, while miR-34a downregulates PD-L1, enhancing anti-tumor immunity." (PMID 39911397, 2025). "ICI involves the use of antibodies that can block inhibitory checkpoints (like CTLA-4, PD-L1, PD-1) on immune cells, allowing these cells to remain active and attack tumor cells." (PMID 41024300, 2025). "In patients, RT plus anti‐CTLA‐4 induced tumor regression, but resistance occurred due to PD‐L1 upregulation; adding anti‐PD‐L1 overcame this resistance and led to durable responses." (PMID 40900811, 2025). "For example, immune checkpoint inhibitors target proteins, such as PD-1, PD-L1, and CTLA-4, which tumor cells exploit to evade immune responses." (PMID 40870970, 2025). "Combining RON inhibitors with anti-CTLA-4 therapy showed a 92% clinical benefit in PyMT-NP tumor models, including significant tumor shrinkage." (PMID 40281554, 2025). "These therapies target immune inhibitory pathways, such as cytotoxic T-lymphocyte-associated antigen 4 (CTLA-4) and programmed cell death protein 1 (PD-1), to enhance anti-tumour immune responses." (PMID 39941557, 2025). "These cells express potent immunosuppressive mediators, including IL-10, TGF-β, and CTLA-4, which collectively suppress the maturation and activity of cytotoxic T cells, thereby facilitating immune evasion by tumor cells." (PMID 40871003, 2025). "Tumours, especially in immune-privileged sites like the CNS, upregulate CTLA-4 at barriers to limit T-cell infiltration." (PMID 40361472, 2025). "ICIs have revolutionized cancer therapy by targeting inhibitory pathways such as PD-1, PD-L1, and CTLA-4, restoring T-cell activity and enhancing tumor elimination." (PMID 40165967, 2025). "- Overcoming resistance in tumors with low PD-L1 or CTLA-4 expression.- Managing autoimmune side effects due to broad T-cell activation.- Effectiveness can vary across different tumor types and patients." (PMID 40630962, 2025). "In preclinical mouse tumor models, the safety and efficacy of combination therapies such as curcumin with anti-CTLA-4 antibodies have also been evaluated, as curcumin promotes PD-L1 for ubiquitin degradation." (PMID 40087690, 2025). "Although anti-CTLA-4 antibodies can prime new tumor-specific T cells, it is plausible that most responders had a preexisting CD8+ T-cell response." (PMID 41312368, 2025). "recently developed Fc-optimized anti-CTLA-4 antibodies that remodel tumor vasculature and increase TA-HEVs, significantly enhancing the infiltration of CD4+ and CD8+ T cells." (PMID 41331976, 2025). "For HCC, studies indicate that combining PD-1/PD-L1 and CTLA-4 inhibitors can significantly enhance T-cell activation and restore anti-tumor immune responses, particularly in patients who exhibit poor responses to monotherapy." (PMID 40918452, 2025). "There is a strong correlation of CTLA-4 levels and enhanced tumor infiltration with Treg and inhibitory macrophages." (PMID 40895574, 2025). "In terms of HCC, tumor-resident Tregs express several immune checkpoints, including TIGIT and CTLA4, and the increased percentage of Tregs is closely related to the tumor stage and tumor size of HCC." (PMID 40186298, 2025). "Cadonilimab, a PD-1 and CTLA-4 bispecific antibody, activates the anti-tumor immune response more comprehensively." (PMID 40463875, 2025). "Contrasting with these studies of anti-CTLA-4 antibody-mediated inhibitory effects on T-cell activation were clear demonstrations of anti-tumour activity in several mouse models, supporting the potential for treating patients with anti-CTLA-4 antibodies." (PMID 40265076, 2025). "Cancer treatment has been revolutionized by immune checkpoint inhibitors, such as anti-PD-1 and anti-CTLA-4 therapies, which enable the immune system to target tumor cells." (PMID 39949765, 2025).
tumor (continued). "A hallmark of T cell exhaustion is the sustained expression of markers such as Tox, Ctla4, Entpd1, Pdcd1, and Havcr2, many of which were enriched in the tumor-infiltrating subset (Cluster 5)." (PMID 40229241, 2025). "For instance, combination therapies using LIGHT agonists with anti-PD-1 or anti-CTLA-4 antibodies have shown enhanced tumor clearance in preclinical models by reinvigorating exhausted T cells and promoting durable anti-tumor immunity." (PMID 40496862, 2025). "For this purpose, a new group of Alb-R26Met tumor-bearing mice was generated to constitute cohorts treated with a combinatorial regiment of anti-PDL1+anti-CTLA4 together with either Decitabine or MEK+BCL-XL blockage." (PMID 40124507, 2025). "ICIs enhance anti-tumour immunity by targeting the inhibitory checkpoint receptors CTLA-4, PD-1, PD-L1, and LAG-3." (PMID 40265076, 2025). "Commonly investigated immunotherapy biomarkers include PD-L1, microsatellite instability (MSI), CTLA-4, and tumor-infiltrating lymphocytes (TILs)." (PMID 40717879, 2025). "Immunomodulators, including certain immune checkpoint inhibitors (such as PD-1 and CTLA-4 inhibitors), have been incorporated into ADCs designs to enhance immune responses within the tumor microenvironment." (PMID 40469310, 2025). "NPs, such as liposomes and polymeric carriers, ensure tumor-specific delivery of ICIs like anti-PD-1 or anti-CTLA-4 antibodies." (PMID 40230883, 2025). "Checkpoint inhibitors, such as PD-1 and CTLA-4 blockers, function by preventing interactions between PD-1 and PD-L1 on tumor cells or between CTLA-4 and CD80+ on antigen-presenting cells." (PMID 40517176, 2025). "The observed survival benefit is likely driven by the synergistic activation of T-cells via dual blockade of the PD-1/PD-L1 and CTLA-4 pathways, potentially enhancing T-cell priming, infiltration, and tumor microenvironment modulation." (PMID 40963599, 2025). "Blocking integrin interactions can reduce PD-1 and CTLA-4 expression, thereby enhancing T cell activation and anti-tumor responses." (PMID 39911388, 2025). "Immunotherapy with antibodies blocking the PD‐1/PD‐L1 axis and CTLA‐4 can restore and improve the anti‐tumour T cell‐mediated immunity." (PMID 39789732, 2025). "Block inhibitory pathways (e.g., PD-1, CTLA-4) to enhance T-cell activation and anti-tumor immunity." (PMID 40881676, 2025). "Other studies have shown that the expression of immune checkpoint molecules such as PD-1, PD-L1, and CTLA-4 can vary significantly across different cell populations within the tumor, highlighting the complexity of immune regulation in the TME." (PMID 40003691, 2025). "ICIs, such as PD-1 and CTLA-4 blockers, work by removing the "brakes" on immune cells, allowing T cells to more effectively recognize and attack tumor cells." (PMID 40050933, 2025). "Preclinical data indicate that targeting CTLA-4 can disrupt this interaction, restore T-cell activation, and enhance anti-tumor immunity, supporting the exploration of CTLA-4 inhibitors as a potential therapeutic option, particularly in PD-1-refractory cHL." (PMID 40806636, 2025). "Tumor antigen-specific T cells within the tumor microenvironment often exhibit a dysfunctional phenotype due to increased expression of inhibitory receptors such as CTLA-4 and PD-1, leading to reduced antitumor activity." (PMID 39325360, 2025). "Tumor inhibition was significantly more effective when vaccination with MUC1 mRNA-loaded NLE was combined with silencer blockade of CTLA-4." (PMID 40943370, 2025). "For example, the combination of anti-PD-1 and anti-CTLA-4 with OAV expressing GM-CSF inhibited tumor growth and prolonged survival in a TNBC mouse model." (PMID 40104170, 2025). "While the PD-1/PD-L1 axis is one of the best-characterized checkpoints, CTLA-4 and others also contribute to immune homeostasis, and their dysregulation within the tumor microenvironment (TME) further amplifies immunosuppression." (PMID 41204180, 2025).
tumor (continued). "Herpes simplex virus G47Δ-mIL12 has been noted in inducing anti-tumor immunity and the triple combination of G47Δ-mIL12, anti-PD-1 and anti-CTLA-4 extended survival of a GBM mouse model." (PMID 41210942, 2025). "A study found that CTLA-4 on Tregs interacted with CD80 expressed on dendritic cells within the lymph nodes surrounding the tumor to regulate CD4+ T cell infiltration into tumors." (PMID 40861801, 2025). "Depletion of specific factors such as CD73 on these hybrid cells can sensitize the tumor and metastatic colonization to anti-CTLA-4 ICB." (PMID 41550427, 2025). "Replimune-2 (RP2) is a modified HSV-1 virus similar to RP1, but with the addition of anti-CTLA-4 antibody-like molecules designed to locally block CTLA-4 within tumor microenvironment." (PMID 41148835, 2025). "These checkpoints, such as PD-1/PD-L1 and CTLA-4/B7-1/B7-2, regulate immune responses but can also prevent T cells from destroying tumor cells." (PMID 40167762, 2025). "Here, we found that anti-PD1 alone or combined with anti-CTLA-4 delayed tumor growth significantly compared with anti-CTLA-4 alone, and adding OXi8007 to the combined regimen provided significantly enhanced overall survival, though no cures." (PMID 40075618, 2025). "Immune checkpoint inhibitors (ICIs), such as CTLA-4, PD-1, and PD-L1, inhibit the proliferation of tumor-specific T cells and induce their depletion." (PMID 40260303, 2025). "In particular, the data indicate a stronger immunosuppressive role of CD80 compared to CD86 in a tumor tissue context, suggesting the exploration of anti-CTLA-4 and anti-CD80 antibody combinations in animal models." (PMID 40725864, 2025). "Another preclinical research revealed that the group receiving anti-CTLA-4 prior to radiotherapy experienced a better tumor response compared to the group receiving anti-CTLA-4 after radiotherapy." (PMID 40475019, 2025). "Tumor-derived factors induce high miR-155 in Tregs, which post-transcriptionally silences CTLA-4 mRNA." (PMID 40647470, 2025). "By targeting regulatory pathways such as PD-1, PD-L1, and CTLA-4, ICIs restore antitumor T-cell activity, improving survival outcomes across several tumor types." (PMID 40647391, 2025). "ICIs enhance immune activation by blocking inhibitory receptors, such as CTLA-4 and PD-1/PD-L1, enabling immune cells to target and attack tumor cells." (PMID 40242775, 2025). "Research has found that TMB-H tumours generally respond better to immune checkpoint inhibitors (such as PD-1/PD-L1 and cytotoxic T lymphocyte antigen 4 (CTLA-4) inhibitors)." (PMID 39895499, 2025). "In the Bacteroides–CTLA-4 model, T cell responses against B. thetaiotaomicron and B. fragilis were correlated with tumor regression." (PMID 41472726, 2025). "CTLA-4 inhibitors, such as ipilimumab, have been developed to block this checkpoint and potentiate anti-tumor immunity." (PMID 40808954, 2025). "The system enhances tumor targeting via the Fenton reaction and, when combined with CTLA-4 blockade, suppresses tumor growth and metastasis while boosting antitumor immunity." (PMID 40520550, 2025). "We have previously demonstrated the ability of FLIM to assess the immune response to tumor development and to the anti-CTLA-4 therapy by the measurements of the fluorescence lifetime of NAD(P)H in fresh lymphoid tissue." (PMID 39851525, 2025). "In a striatal tumor model, VEGF-C overexpression induces meningeal lymphangiogenesis, displaying a synergy effect with anti-PD-1/cytotoxic T-lymphocyte-associated protein 4 (CTLA-4) therapy, which can be abolished by CCL21/CCR7 blockade." (PMID 41511312, 2025). "Tumor volume at day 21 was significantly reduced in CT26-mock tumors treated with anti-CTLA-4 antibody, either alone or in combination with anti-NKG2D antibody, compared to the isotype control antibody group." (PMID 40558520, 2025).